AANAT (aralkylamine N-acetyltransferase)
Description:
Controls the night/day rhythm of melatonin production in the pineal gland. Catalyzes the N-acetylation of serotonin into N-acetylserotonin, the penultimate step in the synthesis of melatonin.
Synonyms: SNAT; DSPS
Tractability: No criterion of Open Targets' tractability assessment is met for any kind of drug.
Target class: Enzyme; Transferase
Gene: Protein-coding gene on chromosome 17 (76,452,749 to 76,470,122, forward strand). Ensembl gene ENSG00000129673.
Subcellular location: Cytoplasm
Subcellular location (Human Protein Atlas): Cytosol
Pathways (Reactome):
Metabolism: Serotonin and melatonin biosynthesis
Gene Ontology:
Molecular function: aralkylamine N-acetyltransferase activity; protein binding; 14-3-3 protein binding; acyltransferase activity, transferring groups other than amino-acyl groups; AP-3 adaptor complex binding; arylamine N-acetyltransferase activity; N-acetyltransferase activity
Biological process: cellular response to cAMP; circadian rhythm; melatonin biosynthetic process; N-terminal protein amino acid acetylation; indolalkylamine biosynthetic process; photoperiodism; response to calcium ion; response to cAMP; response to copper ion; response to corticosterone; response to cytokine; response to insulin; response to light stimulus; response to peptide; response to prostaglandin E; response to zinc ion
Cellular component: cytoplasm; cytosol; perinuclear region of cytoplasm
Genetic constraint (gnomAD): Loss-of-function variants: 11 observed, 14.18 expected, observed/expected ratio (o/e) 0.78, 90% interval 0.49 to 1.28. The upper end of that interval is the gene's LOEUF score, 1.28, which puts it in group 5 of 6, group 1 being the genes least tolerant of losing a copy. Missense variants: 286 observed, 265.23 expected, observed/expected ratio (o/e) 1.08, 90% interval 0.98 to 1.19. Synonymous variants: 139 observed, 119.78 expected, observed/expected ratio (o/e) 1.16, 90% interval 1.01 to 1.34.
Homologues: Orthologues: chimpanzee AANAT (98% identical), macaque AANAT (92% identical), mouse Aanat (83% identical), rat Aanat (83% identical), rabbit AANAT (81% identical), guinea pig AANAT (80% identical), dog AANAT (79% identical), pig AANAT (74% identical), tropical clawed frog aanat (67% identical), zebrafish aanat1 (67% identical).
Diseases named in the same sentence as AANAT in open-access papers:
AANAT is named in the same sentence as 34 diseases in open-access papers, as found by Europe PMC text mining. Sharing a sentence is not in itself a finding about the gene and the disease. The quoted sentences say what the papers report.
colorectal cancer (2 papers, 2017 to 2024). A primary or metastatic malignant neoplasm that affects the colon or rectum. "According to current study, O-GlcNAcylation of YY1 targets SLC22A15 and AANAT, which promotes carcinogenesis in colorectal cancer cells." (PMID 39050579, 2024).
depression (2 papers, 2011 to 2021). "The present results provide evidence that AANAT gene variants play a role in the pathophysiology of depression and support the hypothesis of the MEL signaling pathway in depression." (PMID 33981243, 2021). "Additionally, arylalkylamine N-acetyltransferase (AANAT) polymorphisms have been reported associated with depression, perhaps through their influence upon N-acetylserotonin or melatonin synthesis." (PMID 21827647, 2011).
glioma (2 papers, 2022 to 2026). A benign or malignant brain and spinal cord tumor that arises from glial cells (astrocytes, oligodendrocytes, ependymal cells). "In this study, transcriptomic data from TCGA, CGGA, and GTEx were integrated to characterize the expression patterns of melatonin receptors (MTNR1A and MTNR1B) and biosynthetic enzymes (AANAT and ASMT) across normal brain tissue, lower-grade glioma and glioblastoma." (PMID 42286740, 2026).
Hepatic fibrosis (2 papers, 2021 to 2022). The presence of excessive fibrous connective tissue in the liver. "In the multidrug resistance gene 2 knockout (Mdr2−/−) mice, administration of the AANAT antagonist miR-200b attenuated the expression of AANAT and melatonin, resulting in increased biliary proliferation, angiogenesis, and hepatic fibrosis." (PMID 36497043, 2022). "In PSC, increased melatonin reduces biliary hyperplasia and liver fibrosis by overexpressing arylalkylamine N-acetyltransferase (AANAT) in the pineal gland." (PMID 34299246, 2021).
autism (1 paper, 2019). Persistent deficits in social interaction and communication and interaction as well as a markedly restricted repertoire of activity and interest as well as repetitive patterns of behavior. "Genetically, autism-associated mutations have been found in genes encoding the key enzymes of melatonin synthesis, Aralkylamine N-acetyltransferase (AANAT), and Acetylserotonin O-methyltransferase (ASMT), as well as a reduced expression of the gene encoding AANAT in ASD." (PMID 30804889, 2019).
cholangiocarcinoma (1 paper, 2016). A carcinoma that arises from the intrahepatic biliary tree (intrahepatic cholangiocarcinoma) or from the junction, or adjacent to the junction, of the right and left hepatic ducts (hilar cholangiocarcinoma). "Downregulation of expression of a GNAT enzyme from a different family—arylalkylamine N-acetyltransferase (AANAT)—correlated with development of the biliary cancer, cholangiocarcinoma." (PMID 27367672, 2016). "Elevated AANAT expression has showed an inhibitory effect on the development of cholangiocarcinoma and increased apoptosis of the cholangiocarcinoma cell line in an in vitro assay." (PMID 27367672, 2016).
Cognitive impairment (1 paper, 2023). Abnormal cognition is characterized by deficits in thinking, reasoning, or remembering. "EA attenuates cognitive impairment in stroke rats by regulating endogenous melatonin secretion through synthesizing the aralkylamine N-acetyltransferase gene in the pineal gland." (PMID 37735698, 2023).
hepatocellular carcinoma (1 paper, 2022). A malignant tumor that arises from hepatocytes. "Do all cancer cells transfer 14-3-3zeta in exosomes to t cells in order to upregulate AANAT, which, when coupled to kynurenine activation of the AhR, increases the NAS/melatonin ratio, as indicated by data in hepatocellular carcinoma exosomes ?" (PMID 36613754, 2022).
liver cancer (1 paper, 2022). An epithelial or non-epithelial malignant neoplasm that arises from the liver. "Overall, the survival analysis based on the DEGs suggests that the expression of POSTN, HTRA3, LAYN, AFM and AANAT are associated with the outcomes of patients with liver cancer." (PMID 35676936, 2022). "Upregulation of POSTN, LAYN and HTRA3 and downregulation of AANAT and AFM were positively related to poorer overall survival in human liver cancer." (PMID 35676936, 2022). "Moreover, lower expression of AANAT (OS HR = 0.5, 95% CI = 0.35–0.71, p = 7.6e-05; DSS HR = 0.34, 95% CI = 0.22–0.54, p = 8.2e-07) and AFM (OS HR = 0.48, 95% CI = 0.33–0.69, P = 6e-05; DSS HR = 0.36, 95% CI = 0.2–0.64, p = 0.00028) were strongly associated with poorer outcomes in liver cancer." (PMID 35676936, 2022).
pineal tumor (1 paper, 2021). "The characteristics of pineal tumor cells in vitro have been confirmed by culturing pineal tumor cells in vitro and measuring the mRNA expression of protein genes such as TPH, AANAT, and HIOMT." (PMID 33673851, 2021).
schizophrenia (1 paper, 2022). A major psychotic disorder characterized by abnormalities in the perception or expression of reality. "One RCT in 120 patients with schizophrenia on antipsychotics reported that ramelteon 8 mg as add-on medication significantly increased the night-time melatonin, serum arylalkylamine N-acetyltransferase (AANAT), and urinary 6MTas levels as compared to only antipsychotics without the add-on ramelteon." (PMID 35115662, 2022).
tumor (8 papers, 2017 to 2026). "Expression of AANAT, ASMT, MTNR1A and MTNR1B progressively declined with increasing tumour grade and was associated with poor prognosis." (PMID 42286740, 2026). "Metabolic genes CYP1B1, AANAT, ADH5, and ALDH3A2, associated with the serotonin and melatonin biosynthesis pathway, contribute to tumour growth, immune modulation, and altered metabolic states in the TME." (PMID 39457550, 2024). "In vitro assays demonstrated that two specific ketones (2-pentanone and 2-HEP) reduce tumor cell viability, which was also correlated with increases in aralkylamine N-acetyltransferase (AANAT) and tyrosine hydrogenase (TH)." (PMID 35807522, 2022). "AANAT and TH are rate-limiting enzymes that produce melatonin and dopamine, which have been shown to have a role in tumor suppression." (PMID 33806757, 2021). "Among them, the expression of TIPIN, TIMELESS, ARNTL2, ARNTL, and AANAT are positively correlated with the infiltration level of tumor‐infiltrating lymphocytes in pan‐cancer, respectively." (PMID 31927791, 2020). "Furthermore, in vitro analyses showed upon treatment with 2-HEP and 2-PEN, hypothalamic neuronal cells had reduced tumor cell viability accompanied with elevated levels of aralkylamine N-acetyltransferase (AANAT) and tyrosine hydrogenase (TH)." (PMID 33806757, 2021).
cancer (4 papers, 2017 to 2023). A tumor composed of atypical neoplastic, often pleomorphic cells that invade other tissues. "Cancer cells may target a number of factors that act to regulate the mitochondrial melatonergic pathway in tumor microenvironment cells, including tryptophan uptake, 14-3-3 isoforms, TPH1/2, serotonin uptake/metabolism, acetyl-CoA, AANAT, ASMT, P2Y1r and mGluR5 receptor, as well as the AhR." (PMID 36613754, 2022).
AANAT also shares sentences with these, for which no sentence is quoted: breast carcinoma (2 papers); infection (2); lymphocytic colitis (2); sleep disorder (2); arthropathy (1); autism spectrum disorder (1); bacterial disease (1); colon cancer (1); cutaneous melanoma (1); diabetes (1); Ewing sarcoma (1); gestational diabetes (1); glioblastoma (1); hair diseases (1); intestinal diseases (1); ischemia (1); melanoma (1); microphthalmia (1); mood disorder (1); Sepsis (1); Stroke (1).